C19orf85 (chromosome 19 open reading frame 85)
Gene: Protein-coding gene on chromosome 19 (55,463,001 to 55,464,751, reverse strand). Ensembl gene ENSG00000283567.
Homologues: Orthologues: chimpanzee C19orf85 (99% identical), macaque C19orf85 (92% identical), dog C19orf85 (68% identical), pig C19orf85 (66% identical), rabbit C19orf85 (65% identical), rat C1h19orf85 (65% identical), mouse Gm36210 (63% identical), guinea pig C19orf85 (60% identical).